INSR (insulin receptor)
Diseases named in the same sentence as INSR in open-access papers (continued):
Sharing a sentence is not in itself a finding about the gene and the disease.
myotonic dystrophy type 1 (3 papers, 2016 to 2025). Steinert disease, also known as myotonic dystrophy type 1, is a muscle disease characterized by myotonia and by multiorgan damage that combines various degrees of muscle weakness, arrhythmia and/or cardiac conduction disorders, cataract, endocrine damage, sleep disorders and baldness. "Abnormal expression of the insulin receptor gene may play a role in the development of cancer in patients with type 1 myotonic dystrophy." (PMID 41018201, 2025). "In our 2012 report, we found that the overexpression of Stau1 was able to reverse key splicing defects, for example, the missplicing of exon 11 of INSR and the intronic retention event in the CLC1 pre-mRNA, in the neuromuscular disorder Myotonic Dystrophy Type 1 (DM1)." (PMID 27695661, 2016).
prostate tumour (3 papers, 2012 to 2019). "And notably, an increased ratio of INSR/IGF1R expression has recently been described in prostate tumours and adjacent tissue, which suggests specifically that insulin signalling plays a key role in these tumours." (PMID 23573093, 2013). "In addition, many tumour types, including prostate tumours, upregulate the expression of related insulin receptor (INSR), IGF-1 receptor (IGF-1R), and hybrid INSR/IGF-1Rs further promoting insulin-driven cancer survival pathways." (PMID 23573093, 2013).
psoriasis (3 papers, 2021 to 2025). An autoimmune condition characterized by red, well-delineated plaques with silvery scales that are usually on the extensor surfaces and scalp. "Tumor necrosis factor-α (TNF-α), a key cytokine in the pathogenesis of psoriasis, impairs insulin signaling by inhibiting the tyrosine kinase activity of the insulin receptor and reducing adiponectin secretion." (PMID 40806666, 2025). "However, in chronic inflammatory conditions like acne and psoriasis, elevated levels of pro-inflammatory cytokines activate the p38MAPK pathway, exacerbating IR by inducing serine phosphorylation of insulin receptor substrates (IRSs)." (PMID 40806666, 2025).
Sepsis (3 papers, 2022 to 2023). Sepsis is defined as life-threatening organ dysfunction caused by a dysregulated host response to infection. "Subsequently, Wang and colleagues demonstrated a role for HMGB1 in sepsis, although it has also been reported to participate in the transcriptional regulation of cancer-related genes such as tumor necrosis factor alpha, E-selectin, breast cancer type 1 susceptibility protein, and insulin receptor." (PMID 37009887, 2023). "Functionally, the pathway involving SQSTM1 and INSR can have a significant impact on tissue damage, systemic inflammation, organ failure, and mortality in experimental sepsis mouse models when either genetically deleted or pharmaceutically inhibited." (PMID 38020710, 2023). "Blocking SQSTM1 by administering neutralizing monoclonal antibodies or deleting the INSR or SQSTM1 genes in bone marrow cells (BMCs) effectively safeguards mice from fatal sepsis." (PMID 38020710, 2023).
SHORT syndrome (3 papers, 2016 to 2022). A rare disorder characterized by multiple congenital anomalies, including short stature, hyperextensibility of joints, ocular depression, Rieger anomaly and teething delay in which the cause of the disease is a mutation in PIK3R1 gene. "Hereditary insulin resistance syndromes include genetic syndromes caused by INSR mutations, SHORT syndromes caused by PIK3R1 abnormalities, and conditions caused by AKT2, TBC1D4, or PRKCE abnormalities." (PMID 36626508, 2022). "We report 5 patients with SHORT syndrome and C-terminal mutations in PIK3R1, encoding the p85α/p55α/p50α subunits of PI3K, which act between INSR and AKT in insulin signaling." (PMID 27766312, 2016).
synovial sarcoma (3 papers, 2018 to 2023). "Interestingly, the combination of ssLMWH with a small-molecule inhibitor of IGF1R/insulin receptor (IR) produced a synergistic antiproliferative effect, abrogated cell motility, and promoted apoptosis in CME-1 synovial sarcoma cells." (PMID 30413079, 2018).
acne (2 papers, 2021 to 2025). An inflammatory process of the sebaceous glands which is characterized by comedones, nodules, papules and/or pustules on the skin. "An exception was the INSR rs1799817 polymorphism, which initially showed a significant association with acne (p = 0.008), suggesting a potential involvement in hyperandrogenic pathways." (PMID 40725495, 2025). "However, the observed association between the INSR rs1799817 polymorphism and the presence of clinical symptoms such as acne may suggest the involvement of this variant in metabolic disturbances, potentially leading to secondary hyperandrogenism." (PMID 40725495, 2025).
anaplastic large cell lymphoma (2 papers, 2015 to 2020). Anaplastic large cell lymphoma (ALCL) is a rare and aggressive peripheral T-cell non-Hodgkin lymphoma, belonging to the group of CD30-positive lymphoproliferative disorders, which affects lymph nodes and extranodal sites. "As a receptor tyrosine kinase of insulin receptor (IR) subfamily, anaplastic lymphoma kinase (ALK), has been validated to play important roles in various cancers, especially in non–small cell lung cancer (NSCLC) and anaplastic large cell lymphoma (ALCL)." (PMID 33384022, 2020).
Anorexia (2 papers, 2020 to 2022). Lack of desire to eat (loss of appetite). "Only GLP1R in the CNS followed a similar tendency with LeptinR and INSR, suggesting that GLP1 induced anorexia possibly directed central pathways." (PMID 32355579, 2020).
Atrophy (2 papers, 2016 to 2020). Any weakening or degeneration, especially through lack of use. "Insulin-like growth factor 1 receptor (IGF1R) and insulin receptor (INSR) were identified as target genes of miR-322 using luciferase reporter assays and played key roles in Dex-induced muscle atrophy." (PMID 32046161, 2020). "To test if improved cell metabolism by sustained activation of the insulin/mTOR pathway prolongs cone survival in the sodium iodate induced model of RPE atrophy, we constitutively activated the pathway in cones at two separate junction points downstream of the insulin receptor." (PMID 26883199, 2016).
Brain atrophy (2 papers, 2018 to 2023). Partial or complete wasting (loss) of brain tissue that was once present. "Moreover, twelve months of HFD in transgenic AD mice reduced blood–brain barrier leakage and brain atrophy, improved cognition, and returned levels of insulin receptor mRNA to that of the normal wild type mice." (PMID 37443828, 2023).
chordoma (2 papers, 2016 to 2022). Chordomas are rare malignant tumors arising from embryonic remnants of the notochord in axial skeleton. "Activation of IGF-1R and INSR is reportedly detectable in ~40% of chordomas and is associated with significant reduction in disease-free survival." (PMID 27200287, 2016). "We suggest that trials incorporating assessment of these parameters should evaluate the effects of combined IGF-1R/INSR and EGFR inhibition in patients with recurrent chordomas." (PMID 27200287, 2016). "In summary, this exceptionally durable response suggests that there may be merit in evaluating combined IGF-1R/INSR and EGFR inhibition in patients with chordomas that recur following failure of local treatment." (PMID 27200287, 2016).
colorectal adenoma (2 papers, 2015 to 2024). An adenoma that arises from the colon or rectum. "This includes exploring how VDR polymorphisms, such as BsmI, and INSR polymorphisms, such as NsiI A/G, influence the transition from colorectal adenoma to carcinoma." (PMID 39201651, 2024). "The absence of a significant correlation between the INSR rs2059806 polymorphism and CRA suggests a limited role of this gene variant in colorectal adenoma susceptibility." (PMID 39201651, 2024).
colorectal tumor (2 papers, 2019 to 2024). "Interestingly, immunohistochemical analysis of human CRC samples revealed that expression of INSR was almost exclusively found in the vasculature of colorectal tumours." (PMID 30559346, 2019).
diabetic encephalopathy (2 papers, 2019 to 2023). A brain disease that is characterized by functional impairment of cognition, cerebral signal conduction, neurotransmission and synaptic plasticity, and underlying structural pathology associated with diabetes. "Aβ is always tangled with insulin signaling pathway in diabetic encephalopathy and stagnates insulin receptor in the cytosol." (PMID 31551793, 2019).
emphysema (2 papers, 2013 to 2024). "Using AT2-specific insulin receptor knockout mice, we verified the causative role of sustained IGF2 signaling activation in AT2s in emphysema development." (PMID 38902841, 2024).
esophageal cancer (2 papers, 2021 to 2024). A primary or metastatic malignant neoplasm involving the esophagus. "Here we examined the utility of the small molecule CDK inhibitor flavopiridol and the insulin-like growth factor 1 receptor/insulin receptor (IGF-1R/IR) targeted agent BMS-754807 in the treatment of esophageal cancer with elevated expression of c-Myc." (PMID 34621175, 2021).
Follicular Cyst (2 papers, 2020 to 2021). Cyst due to the occlusion of the duct of a follicle or small gland. "All 4 patients with pathogenic variants in INSR showed features consistent with PCOS, including numerous follicular cysts within an extensively luteinized stroma associated with dense stromal proliferation." (PMID 33901270, 2021). "Compared with GCs of follicular cysts in cows, a recent study reported that INSR and PI3K were significantly higher expressed in GCs of control antral follicles." (PMID 31480138, 2020).
glucosuria (2 papers, 2021 to 2023). "We also describe the capacity of these compounds to modulate insulin receptor and insulin receptor substrate 1 via PTP inhibition, to promote glucosuria via SGLT2 inhibition and to suppress hyperuricemia." (PMID 35008779, 2021).
Hypercalcemia (2 papers, 2023). An abnormally increased calcium concentration in the blood. "It is likely that both intracellular hypercalcemia and hypophosphatemia alter the insulin receptor expression and response; the contribution of parathyroid hormone is less clear." (PMID 37350980, 2023). "Both intracellular hypercalcemia and hypophosphatemia are likely to affect insulin receptor expression and response." (PMID 37959184, 2023).
hypogonadism (2 papers, 2018 to 2022). A disorder characterized by decreased function of the gonads. "Neuron‐specific disruption of the insulin receptor (IR) gene induced a reduction in serum LH levels followed by hypogonadism in female mice." (PMID 34934398, 2022). "Thus, the site (or sites) of hypogonadotropism seen in neuronal insulin receptor knockout mice is not clear." (PMID 30515210, 2018).
Hypokalemia (2 papers, 2020 to 2023). An abnormally decreased potassium concentration in the blood. "A recent study indicates a negative correlation between potassium levels and 2-h oral glucose tolerance test blood glucose levels due to hypokalemia impairs insulin receptor function and insulin secretion facilitated by glucose." (PMID 33101192, 2020).
Intellectual disability (2 papers, 2023 to 2024). "These genes encoded the androgen receptor (AR), insulin receptor (INSR), alpha-thalassemia/mental retardation, X-linked (ATRX) chromatin remodeler, and the patched protein homolog (PTCH1) involved in the Hedgehog pathway (Hh) for bone development and chondrocyte differentiation." (PMID 37760551, 2023).
kidney failure (2 papers, 2012 to 2015). An acute or chronic condition that is characterized by the inability of the kidneys to adequately filter the blood. "Generation of triple-knockout animals with a genetic deletion of both insulin receptor and IGF-1 receptor in addition to PHB2 (Phb2pko/Insrpko/Igf1rpko) significantly alleviated renal disease, enhanced survival (Fig4D and E), improved kidney function, and delayed the onset of kidney failure (Fig5A)." (PMID 25643582, 2015).
lung adenocarcinoma (2 papers, 2021 to 2024). A carcinoma that arises from the lung and is characterized by the presence of malignant glandular epithelial cells. "As INSR is one of the central factors of MetS, we analyzed overall survival with high and low INSR transcripts among three different chronic health conditions: pancreatic adenocarcinoma, liver hepatocellular carcinoma, and lung adenocarcinoma." (PMID 39731011, 2024).
lymph node metastasis (2 papers, 2019 to 2022). "In the present study, tissue differentiation was significantly associated with INSR, while lymph node metastasis was linked to PD-L1." (PMID 36245982, 2022). "An association of INSR rs1799817 SNP with the risk of lymph node metastasis of patients with AEG was found in some subgroups (ever smoking subgroup: AA vs GG: adjusted P = .002; AA vs GG/GA: adjusted P = .001 and ever drinking subgroup: AA vs GG/GA: adjusted P = .030)." (PMID 31211453, 2019). "However, the association of INSR rs1799817 SNP with a decreased risk of lymph node metastasis in smoking patients with AEG was found." (PMID 31211453, 2019). "In addition, TCF7L2 rs290481 and INSR rs1799817 SNPs may influence the lymph node metastasis in patients with AEG." (PMID 31211453, 2019). "In addition, TCF7L2 rs290481 and INSR rs1799817 SNPs may influence the lymph node metastasis in AEG patients." (PMID 31211453, 2019).
lymphoma (2 papers, 2020). A malignant (clonal) proliferation of B- lymphocytes or T- lymphocytes which involves the lymph nodes, bone marrow and/or extranodal sites. "In lymphoma cells, PRDM15 regulates the transcription of key genes involved in two major metabolic axes required for tumor cell survival: PI3K/AKT/mTOR signaling (InsR and Igf1R) and glycolysis (e.g Pkm, Pfkp, Eno3)." (PMID 32665551, 2020). "The insulin receptor IGF-1R inhibitor BMS536924 was the only drug with a confirmed specific activity against Ba/F3 overexpressing BTKE41K-C481S over a large range of doses, but this was not confirmed in the lymphoma cell line TMD8." (PMID 32272741, 2020).
meningioma (2 papers, 2018 to 2025). A generally slow growing tumor attached to the dura mater. "Analysis of Gene Ontology terms significantly associated with atypical meningioma confirmed up-regulation of categories intuitive of neoplasia such as Insulin receptor signaling pathway, transmembrane receptor protein tyrosine kinase signaling pathway, and base and nucleotide excision repair." (PMID 29558515, 2018).
myopia (2 papers, 2019 to 2022). "RPTOR and VAMP2 are two more genes identified in our study under insulin receptor signaling and were hypermethylated with a significant association with myopia." (PMID 30858441, 2019).
nephrocalcinosis (2 papers, 2025). Nephrocalcinosis is a disorder that occurs when too much calcium is deposited in the kidneys. "It has been shown that mutations in the human INSR gene cause abnormalities in kidney function, most notably hypercalciuria along with nephrocalcinosis." (PMID 40241988, 2025).
oral cancer (2 papers, 2015 to 2020).
Ovarian Hyperandrogenism (2 papers, 2013 to 2021). Increased production of androgens by the ovaries. "The effects of excessive insulin action on the ovary, which appear to be independent of the insulin receptor (INSR), are suggested to drive ovarian hyperandrogenism in common PCOS." (PMID 33901270, 2021).
pancreatic ductal adenocarcinoma (2 papers, 2023). An infiltrating adenocarcinoma that arises from the epithelial cells of the pancreas. "However, a previous study showed that let-7 family regulated the expression of components of the INSR/IGF1 pathway in individuals with pancreatic ductal adenocarcinoma." (PMID 37958657, 2023).
partial lipodystrophy (2 papers, 2021 to 2023). Loss and redistribution of subcutaneous and/or visceral adipose tissue from specific regions of the body. "Of the 9 patients, 4 had a proven INSR variant, 4 had partial lipodystrophy (3 associated with known genetic variants), and 1 had a heterozygous pathogenic variant in AKT2 (previously reported in 4, 17, 20-29)." (PMID 33901270, 2021).
periodontitis (2 papers, 2022 to 2025). An acute or chronic inflammatory process that affects the tissues that surround and support the teeth. "Oxidative stress, which is elevated in periodontitis, can also impair insulin signaling by causing damage to the insulin receptor and other key components involved in glucose metabolism." (PMID 40136728, 2025). "As immune cell, hepatocytes were found to be correlated to INSR in both periodontitis and COPD in the current study." (PMID 35676670, 2022). "R3HDM was positively correlated with Th1 cells in both diseases, while INSR was positively correlated with Hepatocytes in periodontitis and COPD." (PMID 35676670, 2022). "Therefore, INSR and related hepatocytes and/or hepatocyte growth factors might be a shared genetic and immunological marker, especially in smokers affected by periodontitis and COPD." (PMID 35676670, 2022). "R3HDM was positively correlated with Th1 cells in both diseases, while INSR was positively correlated with Hepatocytes in periodontitis and COPD, supporting a potential pathophysiological relationship between periodontitis and COPD." (PMID 35676670, 2022). "EPB41L4A-AS1, INSR and R3HDM1 are potential crosstalk genes between COPD and periodontitis." (PMID 35676670, 2022). "EPB41L4A-AS1, INSR and R3HDM1 are potential crosstalk genes between periodontitis and COPD." (PMID 35676670, 2022).
renal cell carcinoma (2 papers, 2019 to 2024). "We also quantified the expression of INSR isoforms in renal cell carcinoma (RCC) and normal renal tissue." (PMID 30559346, 2019). "However, clinically, the level of insulin receptor (IR) expression was significantly lower in renal cell carcinoma tissues of patients with tumor stage pT2-4 and/or distant metastases." (PMID 38831128, 2024).
retinal degeneration (2 papers, 2022). Degeneration of the retina. "Interestingly, analysis of INSR expression during retinal degeneration in the rd10 mouse revealed local downregulation of INSR, specifically in horizontal cell axons." (PMID 35444190, 2022). "We show that pharmacological stimulation of INSR signaling with Pi has a disease-modifying effect over the course of retinal degeneration, in line with the beneficial effects of INSR stimulation with insulin reported in other neurodegenerative diseases of the brain and retina." (PMID 35444190, 2022).
sarcopenia (2 papers, 2017 to 2024). Progressive decline in muscle mass due to aging which results in decreased functional capacity of muscles. "In brief, the WAT increase and myosteatosis associated with sarcopenia reduce insulin receptor functions and increase glucotoxicity and cardiovascular mortality." (PMID 39200115, 2024). "In patients with sarcopenia and myosteatosis, insulin receptor sensitivity is highly dysregulated, resulting in insulin resistance." (PMID 39200115, 2024).
skin cutaneous melanoma (2 papers, 2021 to 2022). "Among the hyper-altered cancer types, uterine corpus endometrial carcinoma, skin cutaneous melanoma, and lung squamous cell carcinoma were the most prominent cancer types, which was probably due to the high mutation frequencies of INSR, ACE, and NOS3." (PMID 35513851, 2022). "Analysis of TCGA PanCancer Atlas (skin cutaneous melanoma) showed that patients with a BRAF mutation and high levels of IGF1R and INSR had a worse overall survival." (PMID 34831014, 2021).